APOA1 (apolipoprotein A1)
Diseases named in the same sentence as APOA1 in open-access papers (continued):
Sharing a sentence is not in itself a finding about the gene and the disease.
tumor (continued). "The anti-tumour activity of ApoA1 against several cancer types and its ability to sensitize cancer cells to chemotherapeutic drugs highlights its potential as an adjuvant therapy for cancer patients." (PMID 36050733, 2022). "In mechanism, ApoA1 can promote tumor growth and metastasis by STAT1/p38 MAPK signaling pathway, enhance cancer progression by CD81/C3/PI3K signaling pathway, and induce recurrence by TOP2A." (PMID 36506554, 2022). "AAV-mediated expression of murine APOA1 in WT mice only moderately reduced intraperitoneal Panc02 tumor weight compared with mice receiving control AAVs." (PMID 35577388, 2022). "Evidence for the active lipid metabolism in tumor cells can be provided by quantifying the serum levels of lipid metabolites, such as apolipoprotein A1 (ApoA1), in cancer patients." (PMID 35100989, 2022). "APOA1 expression was negatively correlated with tumor purity (r = − 0.152, p = 1.04e−3), CD8+ T cells (r = − 0.126, p = 8.51e−3), macrophages (r = − 0.144, p = 2.19e−3), neutrophils (r = − 0.164, p = 4.31e−3), and dendritic cells (r = − 0.101, p = 3.17e−3)." (PMID 35858961, 2022). "For instance, ApoA1 takes part in the immunomodulatory effects of tumor microenvironment by enhancing treg response." (PMID 35100989, 2022). "ApoA1, a prominent protein component in HDL, not only has antiapoptotic, anti-inflammatory, and antioxidant functions but also alters tumor-associated macrophages (TAMs) from a pro-tumor M2 to an antitumor M1 phenotype and modulates regulatory T cells." (PMID 35185898, 2022). "One study shows that in MDA-MB-231 cells, the expression of ApoE or ApoA1 inhibit the growth and migration of tumor cells via preventing EMT, probably through preventing the de novo production of fatty acids and cholesterol entry into BC cells." (PMID 36506554, 2022). "Next, and as a consequence of the data obtained from in vitro experiments, we decided to artificially introduce APOA1/rHDL particles into tumor-bearing Apoa1 KO mice." (PMID 35577388, 2022). "A different aspect of the relationship between HDL and cancer, is the anti-tumour activity of ApoA1." (PMID 36050733, 2022). "APOA1 and APOA2 were observed to be associated with E1A binding protein p300 (EP300) and CREB binding protein (CREBBP) which play an important role in tumor metastasis." (PMID 36428687, 2022). "In contrast, GOT2, EHHADH, and APOA1 were significantly negatively correlated with tumor infiltrating immune cells." (PMID 34869039, 2021). "Mechanistically, our discovery analysis indicated that expressions of APOA1, APOC3, and APOA5 are inversely associated with tumor-infiltrating immune cells, and we proposed that they exert an immunomodulatory effect on the tumor microenvironment." (PMID 34226567, 2021). "The lower levels of APOA1, APOC3, and APOA5 expression were associated with higher ESTIMATE immune scores, which indicated an abundance of tumor-infiltrating immune cells." (PMID 34226567, 2021). "In our study, we specifically observed that the expression of APOA-1 protein was significantly associated with hs-CRP, HBsAg, tumor number, Child-Pugh score, and BCLC stage." (PMID 34790226, 2021). "As it exerts anti‐tumor effects, ApoA1 has been used to diagnose and evaluate the prognosis of tumors." (PMID 33336932, 2021). "Further, loading Dox into the present ApoA1-liposome systems enabled a burst release at the tumor location, resulting in enhanced anti-tumor effects and reduced off-target effects." (PMID 33652957, 2021). "Compared with peri-tumor samples, GAD1, SPP1, and WFS1 were significantly upregulated in tumor tissues, and GOT2, EHHADH, and APOA1 were significantly downregulated in tumor tissues." (PMID 34869039, 2021). "We observed a decreased trend in the APOA1 levels (<20 ng/mL) with enhanced tumor stages (stage Ta to T1 and T2)." (PMID 34440141, 2021).
tumor (continued). "GAD1, SPP1, and WFS1 were upregulated, whereas GOT2, EHHADH, and APOA1 were downregulated in HCC samples compared with peri-tumor controls, and this was consistent with the results in the ICGC, GSE14520, GSE54236, GSE107170, and GSE36376, validation datasets." (PMID 34869039, 2021). "Lower APOA1, APOC3, and APOA5 expressions were associated with higher ESTIMATE immune scores, indicating an abundance of tumor-infiltrating immune cells." (PMID 34226567, 2021). "This is further substantiated by functional studies that have shown APOA1 to play important roles in tumor growth, angiogenesis, invasion, and metastasis." (PMID 34440141, 2021). "They provided evidence that ApoA1 reduced tumor angiogenesis and recruited tumor cell targeting macrophages and CD8+ cytotoxic T cells, thereby altering the tumor microenvironment to one less permissive for tumor development." (PMID 32411725, 2020). "In conclusion, anti-apoA-1 antibodies seem to have a role in blocking tumoral cell proliferation and survival, by activating a major tumor suppressor protein and by modulating the inflammatory and oxidative stress response." (PMID 33245719, 2020). "Others have reported that synthetic ApoA1 mimetic peptides, which replicate the amphipathic properties of ApoA1, also exhibit anti-tumor properties, when used at pharmacological concentrations." (PMID 32411725, 2020). "First, studies have shown that low ApoA-1 concentrations inhibit tumor progression through its anti-inflammatory effects." (PMID 32391278, 2020). "Fourth, ApoA-1 inhibits tumor angiogenesis by other means to inhibit tumor growth, but its specific mechanism is not fully understood." (PMID 32391278, 2020). "What differentiate these cell lines is the unlimited and uncontrolled proliferation capacity of tumor cells which appears to be a requirement for the differential cytotoxic effect of anti-apoA-1 antibodies." (PMID 33245719, 2020). "Third, ApoA-1 influences the immune cell response to tumours via the modulation of cholesterol content in membrane lipid rafts." (PMID 30486825, 2018). "ApoA-1 has anti-inflammatory, anti-apoptotic, and antioxidant properties and inhibits the formation of tumour vessels." (PMID 30486825, 2018). "Increased APOB/APOA1 ratio significantly associated with nodal metastases (P = 0.010), high tumor necrosis percentage (P = 0.041), and decreased APOB/APOA1 ratio with cholesterol-lowering medication (P = 0.015)." (PMID 28710487, 2017). "In vitro experiments showed that ApoA-1 can inhibit tumor cell proliferation through cell cycle arrest and promote apoptosis through down regulating mitogen-activated protein kinase (MAPK) pathway." (PMID 27683106, 2016). "Our present study explored the clinical significance of serum ApoA-1 levels in HCC patients, and the potential mechanism mediated by ApoA-1 in tumor progression." (PMID 27683106, 2016). "Predictive factors in the models included tumor length, tumor circumferential extent, age, and ApoA1." (PMID 26646794, 2016). "Tumor length, tumor circumferential extent, and ApoA1 were predictive factors for good tumor regression (TRG 0-1) and good down-staging, whereas young age was only associated with good down-staging." (PMID 26646794, 2016). "The nomogram demonstrated that tumor length and ApoA1 shared the largest contribution to good regression, followed by tumor circumferential extent." (PMID 26646794, 2016). "We investigated the correlation between serum ApoA-1 level, tumor recurrence, and death of patients in the training cohort." (PMID 27683106, 2016). "The circulating tumor cell (CTC) levels were significantly higher in patients with low serum ApoA-1 compared with those with high serum ApoA-1 levels (4.03 ± 0.98 vs. 1.48 ± 0.22; p=0.001)." (PMID 27683106, 2016). "Considering the convenience of serum ApoA-1 analysis, there is potential for ApoA-1 to be used as a marker for tumor recurrence and treatment response surveillance." (PMID 27683106, 2016).
tumor (continued). "In predicting good down-staging, tumor circumferential extent showed the greatest contribution, followed by tumor length, Age, and ApoA1." (PMID 26646794, 2016). "Apolipoprotein A1 (ApoA1) is the major apoprotein constituent of high-density lipoprotein (HDL) that can play important roles in tumor invasion and metastasis." (PMID 26537097, 2015). "Recent findings revealed the crucial roles of ApoA1 in inflammation, tumor growth, angiogenesis, invasion and metastasis." (PMID 26537097, 2015). "A recent fascinating study reveals an overall protective ability of HDL, specifically APOA1, to induce tumor suppression through both innate and adaptive immune processes in multiple animal tumor models." (PMID 26537097, 2015). "Apolipoprotein A1 (ApoA1) is the major apoprotein constituent of high-density lipoprotein that can play important roles in tumor invasion and metastasis." (PMID 26537097, 2015). "Both ApoA-1 and metformin interact with tumor-suppressive liver kinase B1 to activate adenosine monophosphate-activated protein kinase." (PMID 24886453, 2014). "Tumors spots for hemoglobin, apolipoprotein A1, serum albumin, and alpha-2 globulin were five times larger than the same spots from non-tumorous extracts." (PMID 21470419, 2011). "In a HepG2 tumor-bearing humanized mouse model, apoA1-bExo enabled improved tumor selectivity and cellular uptake via the scavenger receptor class B type 1 (SR-B1), facilitating efficient cytosolic delivery of siRNA through an apoA1-mediated selective uptake mechanism." (PMID 40943628, 2025). "Patients with HCC and tumor recurrence exhibited significantly reduced serum ApoA-1 levels." (PMID 40351413, 2025). "Moreover, APOA1 possesses anti-inflammatory properties, modulates immune responses, and inhibits tumor cell proliferation and metastasis by reducing intracellular cholesterol levels." (PMID 41041664, 2025). "Whilst we observe a broadly comparable proteome relative to the human non-diseased brain, we identify cytoplasmic proteins α-trypsin, actin, apolipoprotein A1 and transthyretin which may putatively be associated with the GBM infiltrative tumour margin." (PMID 40617935, 2025). "Additionally, higher serum ApoA-1 levels were observed in patients with reduced levels of circulating tumor cells." (PMID 40351413, 2025). "Notably, APOA1 was abundant in both tumor and normal tissues, highlighting its crucial roles in cellular biology." (PMID 40317014, 2025). "The screening model, integrating ApoA1, ApoA2, lithocholic acid (LCA), and CEA, attained an impressive AUC of 0.995, surpassing the diagnostic accuracy of individual lipids, bile acids, and tumor markers." (PMID 38698075, 2024). "Moreover, the administration of the ApoA1-expressing plasmid significantly decreased lung metastases in 4T1 orthotopically implanted mice following primary tumor resection." (PMID 38566092, 2024). "We also investigated whether macrophages and CD8+ T cells coexist spatially to achieve ApoA1-mediated tumor control." (PMID 37474548, 2023). "We explored whether ApoA1-reprogrammed TAMs could facilitate tissue residency of T cells and establish tumor-specific immune memory." (PMID 37474548, 2023). "To investigate whether locally elevated ApoA1 directly affects TILs, we examined the effect of ApoA1 on cholesterol in tumor-infiltrating CD8+ T cells." (PMID 37474548, 2023). "In addition, and to examine a therapeutic potential of rHDL particles in vivo, we compared Panc02 tumor growth in WT mice, Apoa1 KO mice receiving PBS, and Apoa1 KO mice receiving intravenous injections of rHDL (0.2 mg per injection every other day)." (PMID 35577388, 2022). "The aberrant upregulation of ApoA1 also has a tumor-killing function." (PMID 36506554, 2022). "Moreover, APOA1 expression levels in the plasma of mice with high tumor burden was lower than that of mice with low tumor burden, indicating that the decrease APOA1 expression correlated closely with tumor progression." (PMID 35372408, 2022).
tumor (continued). "Distinctive from ApoC1, ApoB and ApoA1 seem to be tumor suppressors in RCC." (PMID 36506554, 2022). "In the mature immune system, ApoA1 is activated and involved in anti-tumor." (PMID 35100989, 2022). "Thereby, we found that AAV-mediated APOA1 expression did not affect tumor-associated hypoxia, a surrogate marker for tumor oxygenation." (PMID 35577388, 2022). "APOA1 potently suppresses tumor growth through innate and adaptive immune processes." (PMID 35958518, 2022). "Importantly, AAV-APOA1 expression in Apoa1 KO mice significantly reduced Panc02 tumor growth kinetics and tumor weight at experimental end stage." (PMID 35577388, 2022). "Flow cytometric analysis of tumor-associated immune-cell populations showed an increase in MRC1+ M2-polarized macrophages in the Apoa1 KO background, which was not substantially reverted by reintroduction of APOA1." (PMID 35577388, 2022). "APOA1 is easy to detect clinically and has great value as a marker of tumor prognosis." (PMID 35421932, 2022). "ApoA1 can be utilized for early detection whereas ApoA2 can identify tumor stages." (PMID 36506554, 2022). "Interestingly, SFRE upregulated the expression of APOA1 which has been proposed to be a tumour suppressor in several cancers." (PMID 36439419, 2022). "In contrast, GOT2, EHHADH, and APOA1 were associated with better survival outcomes and were significantly downregulated in HCC tissues, as well as positively correlated with tumor stage, grade, age, and sex, suggesting that these three MRGs were tumor suppressor genes." (PMID 34869039, 2021). "A first study identified two lipidic-related ligands of the Vγ9Vδ2 TCR on tumor targets: apolipoprotein A1 (Apo-A1) and ATP synthase/F1-ATPase (high-affinity apo A-I receptor) Apo-A1, abundant in HDL, are required for optimal activation of Vγ9Vδ2 T cells by tumors expressing F1-ATPase." (PMID 34831116, 2021). "Taken together, our findings strongly suggest that APOA-1 is a critical tumor suppressor and APOA-1 hypomethylation could serve as an independent prognostic factor in HCC." (PMID 34790226, 2021). "An experiment showed that the injection of ApoA1 into mice could effectively inhibit tumor growth and metastasis." (PMID 33336932, 2021). "On the other hand, preclinical studies in mouse models have suggested that supra-physiological levels of ApoA1 may have therapeutic potential against tumor growth and metastasis." (PMID 32411725, 2020). "Local tumor expression levels of apolipoprotein A1 might influence inflammatory pathways, which in turn might impact growth of neoplastic cells." (PMID 32998735, 2020). "Whether ApoA1 (injected or overexpressed) or ApoA1 mimetic peptides exert anti-tumor effects by driving the increased formation of HDL-like particles or whether their anti-neoplastic effects are independent of HDL particle formation has not been examined." (PMID 32411725, 2020). "By using different tumor cell lines, including a human melanoma cell line (A375), they demonstrated that supra-physiological levels of ApoA1 may have general anti-neoplastic effects including toward human tumors." (PMID 32411725, 2020). "In addition, several indications suggest a possible involvement of both extrinsic “death receptor” and intrinsic “mitochondria dependent” apoptotic pathways, in the caspase 3-dependent apoptotic effect of anti-apoA-1 antibodies on the tumor cell lines." (PMID 33245719, 2020). "Similarly, preclinical studies demonstrated that the recombinant ApoA1 mimetic peptide 6F reduced tumor burden in mouse models of metastatic lung cancer." (PMID 32411725, 2020). "Age, T stage, tumor location, CEA, monocytes, LMR and ApoA1 could reflect immune cells infiltrating the tumor microenvironment of CRC." (PMID 31300050, 2019). "Many studies have focused on the relationship between ApoA-1 and tumours." (PMID 30486825, 2018).
tumor (continued). "Lastly, ApoA-1 could inhibit tumour cell proliferation through cell cycle arrest and could promote apoptosis in the regulation of the mitogen-activated protein kinase (MAPK) pathway." (PMID 30486825, 2018). "Therefore, the effect of ApoA1 exposure on the ability of SKOV3 cells to invade the extracellular matrix was investigated in a 3D tumor spheroid invasion assay." (PMID 30745873, 2018). "However, proteins which appear to be involved in cellular apoptosis (e.g. POTEF) and tumor suppression (APOA1) were also noted to be up regulated following Oct4A suppression." (PMID 28406185, 2017). "The identified high-density lipoprotein component APOA1, is an LXR/RXR target known to control cholesterol efflux but which also has immune modulating activities, such as promoting polarization of tumor-associated macrophages towards the anti-tumor M1-like macrophage." (PMID 29100312, 2017). "Other up regulated cellular proteins which were identified included the cytoskeletal-related actin binding protein Twinfilin-1 (TWF1) (Rsc 5.1), and the tumor suppression-related proteins Apolipoprotein A-1 (APOA1) (Rsc 5.1) and Eukaryotic release factor 1 (ETF1) (Rsc 2.3)." (PMID 28406185, 2017). "Instead, serum APOB levels or APOB/APOA1 ratio did not significantly associate with tumor stage, suggesting that tumor progression has less impact on these parameters." (PMID 28710487, 2017). "The effect of ApoA-1 on tumor cell apoptosis was also investigated." (PMID 27683106, 2016). "Hence, the final selected predictors in the multivariate model were age, tumor length, tumor circumferential extent, and ApoA1." (PMID 26646794, 2016). "Releasing of tumor cells into circulation is a multiple-step procedure, which including a great number of proteins, and ApoA-1 acts as one of the major molecules involved in this procedure, which could effectively affect the viability of CTCs." (PMID 27683106, 2016). "Recent studies indicated that ApoA-1 could inhibit the formation of tumor vessels, induce an anti-tumor immune microenvironment that prevents tumor progression and serve as a potential therapeutic target for patients with cancer." (PMID 27683106, 2016). "ApoA1 is the main protein component of high density lipoprotein in plasma, which is involved in the formation of most plasma cholesterol esters.This protein potently suppresses tumor growth and metastasis in multiple animal tumor models." (PMID 28224023, 2016). "The role of ApoA-1 in inhibiting the proliferation of tumor cells, as well as promoting apoptosis of cancer cells during tumor cell hematogenous dissemination, are presumably responsible for the high recurrence rate and poor prognosis observed in HCC patients with a low serum ApoA-1 level." (PMID 27683106, 2016). "Differences in APOA1 isoforms and/or conformation between serum and tissue samples as well as tumour heterogeneity may explain for the discrepancies between DIGE and ELISA when compared to immunohistochemistry." (PMID 26463353, 2016). "ApoA1 can play important roles in tumor growth, angiogenesis, invasion and metastasis." (PMID 26537097, 2015). "Similarly, hydrodynamic administration of ApoA1-expressing plasmids through the tail veins of mice significantly impeded the growth of 4T1 orthotopic xenografts and significantly prolonged the survival of tumor-bearing mice." (PMID 38566092, 2024). "Moreover, APOA1 overexpression can reduce tumor growth in vivo." (PMID 38212711, 2024). "Apolipoprotein-A1 is known to have anti-tumor activity and may hinder tumor growth by inhibiting angiogenesis, reducing tumor metastasis and invasion, and regression of tumor size." (PMID 37569650, 2023). "Interestingly, a study reported that curcumin could increase the expression of APOA1 in the sorafenib-treated mice and enhance the antitumor effects of sorafenib through regulating the metabolism and tumor microenvironment." (PMID 36838613, 2023).